GALR2 (galanin receptor 2)
Description:
Receptor for the hormone galanin and GALP. Receptor for the hormone spexin-1. The activity of this receptor is mediated by G proteins that activate the phospholipase C/protein kinase C pathway (via G(q)) and that inhibit adenylyl cyclase (via G(i)).
Synonyms: GAL2-R; GALR-2; GALNR2
Tractability: Small molecule: a structure with a bound ligand is known; a high-quality ligand is known; it belongs to a druggable protein family. Antibody: its Gene Ontology location is reachable by antibodies, with high confidence; UniProt places it where antibodies can reach, with medium confidence; UniProt predicts a signal peptide or a membrane-spanning region. PROTAC: a small molecule that binds it is known.
Target class: Membrane receptor; Peptide receptor (family A GPCR); Family A G protein-coupled receptor; Galanin receptor; Short peptide receptor (family A GPCR)
Gene: Protein-coding gene on chromosome 17 (76,074,781 to 76,077,537, forward strand). Ensembl gene ENSG00000182687.
Subcellular location: Cell membrane
Pathways (Reactome):
Signal Transduction: G alpha (i) signalling events; Peptide ligand-binding receptors
Gene Ontology:
Molecular function: galanin receptor activity; peptide hormone binding; protein binding; G protein-coupled receptor activity; neuropeptide binding
Biological process: galanin-activated signaling pathway; phospholipase C-activating G protein-coupled receptor signaling pathway; positive regulation of transcription by RNA polymerase II; adenylate cyclase-modulating G protein-coupled receptor signaling pathway; feeding behavior; learning or memory; muscle contraction; positive regulation of cytosolic calcium ion concentration; adenylate cyclase-activating G protein-coupled receptor signaling pathway; G protein-coupled receptor signaling pathway; inositol phosphate metabolic process; phosphatidylinositol metabolic process
Cellular component: cilium; membrane; plasma membrane; 9+0 non-motile cilium
Genetic constraint (gnomAD): Loss-of-function variants: 5 observed, 5.35 expected, observed/expected ratio (o/e) 0.93, 90% interval 0.48 to 1.76. That is too few expected variants to judge how well the gene tolerates losing a copy. Missense variants: 561 observed, 501.56 expected, observed/expected ratio (o/e) 1.12, 90% interval 1.04 to 1.2. Synonymous variants: 300 observed, 237.16 expected, observed/expected ratio (o/e) 1.26, 90% interval 1.15 to 1.39.
Homologues: Orthologues: chimpanzee GALR2 (99% identical), macaque GALR2 (95% identical), dog GALR2 (86% identical), pig GALR2 (82% identical), rat Galr2 (82% identical), mouse Galr2 (81% identical), tropical clawed frog galr2 (62% identical), zebrafish galr2a (56% identical), Drosophila melanogaster AstA-R1 (29% identical), Drosophila melanogaster AstA-R2 (26% identical). Paralogues in human: CXCR3 (24% identical), CXCR2 (23% identical), CXCR1 (22% identical), CCR1 (22% identical), CXCR4 (22% identical), CXCR5 (21% identical), CCR3 (21% identical), CCR10 (20% identical), CXCR6 (20% identical), CCR4 (19% identical), ACKR2 (19% identical), CCR5 (19% identical), and 11 more.
Diseases named in the same sentence as GALR2 in open-access papers:
GALR2 is named in the same sentence as 83 diseases in open-access papers, as found by Europe PMC text mining. Sharing a sentence is not in itself a finding about the gene and the disease. The quoted sentences say what the papers report.
depression (23 papers, 2016 to 2026). "First, SPX1 has the capacity to bind Galr2 and Galr3, which are implicated in anxiety and depression-like behaviors in mice." (PMID 31474838, 2019). "The higher relevance of the GalR2, GalR3 and GalR1 gene polymorphisms in stress-induced depression and the galanin system-independent effects of the currently used antidepressants suggest that novel antidepressants acting on GalR1-3 could be developed." (PMID 30627087, 2018). "Activation of GALR1 and GALR3 induces depression-like behaviors, whereas activation of GALR2 inhibits depressive-like behaviors." (PMID 40048451, 2025). "The stimulation of GalR2 by Gal and its agonists has demonstrated promise in reducing IR and depression-like behavior." (PMID 40519702, 2025). "Accordingly, GalR2-knockout mice show depression-like behaviors, while GalR2-overexpressing mice exhibit antidepressant-like behaviors." (PMID 33589739, 2022). "Evidence for collaboration between small neurotransmitter and neuropeptide in the development of depression was also identified in this study, namely a gene–gene–environment interaction between the GalR2 and 5-HTTLPR genes in strongly exposed persons." (PMID 30627087, 2018). "Taken together, galanin receptors GalR1 and GalR2 play a differential role in regulation of depression-like behavior." (PMID 30627087, 2018). "Although GALR2 is known to display a function, particularly in anxiety, depression, and appetite regulation, the further determination of its function would benefit from a more stable and selective agonist that acts only at GALR2." (PMID 26907960, 2016). "We may speculate that subchronic or chronic intranasal treatments with GALR2 and Y1R agonists would be required in pathological models of depression or to achieve long‐lasting effects." (PMID 36599082, 2023). "Thus, the activation of GalR1 and GalR3 results in depression-like behaviors, whereas stimulation of GalR2 leads to antidepressant-like effects." (PMID 33589739, 2022). "Thus, therapeutics that promote the close correlation between dentate neurogenesis and BDNF, as seen under the GALR2 and Y1R agonist combination, maybe the key to preventing or curing depression." (PMID 36599082, 2023). "Moreover, mice with a knockout for the galanin receptor (GalR2) showed anxiety- and depressive-like behaviours, suggesting GalR2 may be involved in the antidepressant-like effects of galanin and may be a valid drug target for depressive disorders." (PMID 36362131, 2022). "SPX, acting as a cognate ligand for GALR2/3, could be involved in anxiety/depression." (PMID 31275244, 2019). "The synthetic SPX-based GALR2-specific agonist, SG2A, plays a dual role in the regulation of appetite and depression-like behaviors." (PMID 32231393, 2020). "Various studies have provided evidence about the role of GALR2 and GALR3 in the mechanism of depression." (PMID 31275244, 2019). "Heterobivalent drugs with GalR1 and GalR2 antagonist pharmacophors may specifically target the GalR1 and GalR2 binding pockets of the GalR1-GalR2 heteroreceptor complex, disrupt their function and represent a new strategy for treatment of depression and anxiety." (PMID 28270751, 2017). "GalR1 and GalR2 are expressed throughout the brain,while GalR3 is confined to the hypothalamus It has been postulated that the dysregulation of the normal interaction between NE and Gal in the amygdala may contribute to stress-related disorders, such as depression, anxiety and PTSD." (PMID 27907151, 2016).
Anxiety (15 papers, 2006 to 2025). Intense feelings of nervousness, tension, or panic often arise in response to interpersonal stresses. "Subsequent studies using GalR2 null mutant mice demonstrated, however, an anxiogenic-like phenotype in the Elevated Plus-Maze and other tests of anxiety." (PMID 35681521, 2022). "Taken together, we propose based in previous and present results carried out in innate models of anxiety a model for the circuit activity modifications induced by GALR2 and NPYY1R coactivation." (PMID 29765307, 2018). "For instance, chronic stress or elevated Tau expression selectively suppresses ventral neurogenesis and promotes anxiety-like behavior, whereas antidepressant treatments such as fluoxetine or GALR2/Y1R agonists restore neurogenesis primarily in the ventral DG and alleviate depressive phenotypes." (PMID 41511343, 2025). "The three galanin receptor subtypes, GALR1, GALR2, and GALR3, are widely distributed in mood-related brain areas such as hypothalamus, central amygdaloid nucleus, and thalamus and may mediate anxiety-associated behavior." (PMID 16623937, 2006). "This GALR2 and NPYY1R coactivation elicited in innate models of anxiety a specific behavioral profile on ethological parameters, increasing rearing and head-dipping and reducing stretch attend postures and freezing, that strongly support anxiolytic actions." (PMID 29765307, 2018). "Thus, our results may provide the basis for the development of heterobivalent agonist drugs targeting GALR2/NPYY1R heteromers, especially in the ITCp-dl of the amygdala for the treatment of anxiety." (PMID 29765307, 2018).
Insulin resistance (6 papers, 2019 to 2025). Increased resistance towards insulin, that is, diminished effectiveness of insulin in reducing blood glucose levels. "GALR2 has potential as a therapeutic target in treating insulin resistance, as its activation alleviates insulin resistance through the P38MAPK/PGC-1α/GLUT4 and AKT/AS160/GLUT4 pathways in mouse skeletal muscle." (PMID 40266928, 2025). "The GALR2 gene is a regulator of insulin resistance, and activation of GALR2 represents a promising strategy against obesity-induced insulin resistance." (PMID 39273703, 2024). "In 2018 it was proven that the activation of GalR2 attenuates insulin resistance in the skeletal muscle of obese mice." (PMID 35052420, 2021). "Also, galanin attenuates depression-like behavior and insulin resistance through the central galanin receptor 2 (GalR2)." (PMID 31231496, 2019). "Therefore, further targeted studies are warranted to clarify whether SPX acts via GALR2 to influence insulin resistance and hepatic metabolism, and to explore the involvement of the FOXO1/PGC-1α pathway in these processes." (PMID 40841811, 2025).
Obesity (6 papers, 2016 to 2025). Accumulation of substantial excess body fat. "Notably, cinchonine, a natural compound, exerted simultaneous inhibitory effects on these pathways (i.e., it significantly downregulated gene expression of Srepbf1, Galr1, and Galr2 in fat tissue), resulting in reduced adipogenesis and mitigated obesity." (PMID 39968178, 2025). "It is known that GALR2 increases during obesity, but different results have been found for GALR3." (PMID 38339044, 2024). "Another research revealed that galanin could regulate the pain threshold in obesity by central galanin receptor-1 and peripheral galanin receptor-2, though the antinociceptive effect of activating the receptors had not been clearly characterized." (PMID 36082069, 2022). "Moreover, spexin has been shown to be a natural ligand for galanin receptor 2/3 (GALR2/3) and plays an important role in feeding behavior, gastrointestinal motility, obesity, diabetes, energy metabolism, endocrine and mental diseases, and cardiovascular function." (PMID 36118333, 2022). "Spexin-mediated mitigating effects on obesity and MASLD in mice on HFD and in PA-induced HepG2 cells were eradicated by M871, proving that spexin, a known GalR2/3 agonist, produces its beneficial effect through the activation of GalR2." (PMID 39968178, 2025).
colorectal cancer (5 papers, 2008 to 2024). A primary or metastatic malignant neoplasm that affects the colon or rectum. "GALR2 hypermethylation showed a sensitivity of 85%, specificity of 95% and accuracy of 98% and the combination of GALR2 or NKX2-5 hypermethylation showed a sensitivity of 90%, specificity of 95% and accuracy of 96% for detecting colorectal cancer." (PMID 18446232, 2008).
epilepsy (5 papers, 2012 to 2026). A brain disorder characterized by episodes of abnormally increased neuronal discharge resulting in transient episodes of sensory or motor neurological dysfunction, or psychic dysfunction. "Interestingly, we were able to provide evidence that GALR2 is potentially an additional gene associated with a recessive form of epilepsy." (PMID 41751541, 2026). "Interestingly, a recent paper suggests GALR2 as a more suitable potential drug target to treat epilepsy, but this literature mining result is currently the only type of evidence supporting the GALR2-epilepsy association in the Open Targets Platform." (PMID 30285606, 2018). "In other galanin receptor systems, opposing effects can be evoked by activation of these G-proteins by the same receptor, for example, in a model of epilepsy, GalR2-Gi activation is antiepileptic and GalR2-Gq is proepileptic." (PMID 22315681, 2012). "For example, galanin, an endogenous ligand for the GPCR galanin receptor type 2 (GALR2), plays an important role in epilepsy." (PMID 35883418, 2022). "For example, the evidence collected in the Open Targets platform suggests that galanin, an endogenous ligand for the GPCR galanin receptor type 2 (GALR2), plays an important role in epilepsy, one of the most common neurological disorders (overall score = 1.0)." (PMID 30285606, 2018).
neuroblastoma (5 papers, 2015 to 2024). Neuroblastoma (NB) is the most common solid, extracranial childhood tumor. "While some studies have shown GALR2 to be proproliferative, others indicate that reintroduction of GALR2 into tumor cell lines established from pheochromocytoma, neuroblastoma and HNSCC are susceptible to galanin-mediated apoptosis and/or growth inhibition." (PMID 26251921, 2015).
breast carcinoma (4 papers, 2008 to 2024). "GALR2 is hypermethylated in colon cancer and breast cancer but rarely in prostate cancer." (PMID 18446232, 2008). "Compared to adjacent normal breast, all 6 genes except NKX2-5 showed higher methylation in breast cancer by t-test analysis (P<0.001 for DPYS and EGFR5 P = 0.01 for SLC16A12; P = 0.002 for TOX; P = 0.003 for GALR2)." (PMID 18446232, 2008). "Finally, SLC16A12, GALR2, TOX, SPOCK2, EGFR5 and DPYS are candidate biomarkers for breast cancer (methylation range 33%–79%) with the combination of EGFR5 or TOX hypermethylation showing a sensitivity of 92% and specificity of 92%." (PMID 18446232, 2008). "Furthermore, galanin receptor 2 (GALR2) is a G protein-coupled receptor that induces tumor growth and proliferation in SCCHN (squamous cell carcinoma of the head and neck), and GALR2 has been identified as a novel target and biomarker for prostate, colon, and breast cancer screening." (PMID 36146599, 2022).
head and neck cancer (3 papers, 2012 to 2024). A primary or metastatic malignant neoplasm affecting the head and neck. "In the context of tumors, GAL was found to promote tumor invasion via binding to its receptor, GALR2, in head and neck cancer." (PMID 36039037, 2023). "GALR2 has been proposed as a therapeutic target in head and neck carcinoma and is an active area of study." (PMID 23251904, 2012).
cardiac hypertrophy (2 papers, 2022 to 2025). "Phenotypic analysis of mice deficient for GalR2 reveals a role for GalR2 in coordination of cardiac hypertrophy, fibrosis and mitochondrial ROS status." (PMID 35431947, 2022). "In vivo, genetic suppression of GalR2 promotes cardiac hypertrophy, fibrosis and mitochondrial oxidative stress in the heart." (PMID 35431947, 2022). "We provide the first evidence that genetic suppression of GalR2 promotes cardiac hypertrophy, fibrosis and mitochondrial oxidative stress in vivo." (PMID 35431947, 2022).
colitis (2 papers, 2016 to 2021). Inflammation of the colon. "Interestingly, in the previous study we have observed a significant decrease in the expression of galanin, GalR1, GalR2 and GalR3 receptors (in the mucosa, tunica muscularis and lymphocytes) in the porcine descending colon wall affected by dysentery associated colitis." (PMID 27175780, 2016).
fatty liver disease (2 papers, 2023 to 2026). A reversible condition wherein large vacuoles of triglyceride fat accumulate in liver cells via the process of steatosis. "Studies have demonstrated that these beneficial effects were eliminated by the GALR2 antagonist M871 in mice fed a high-fat diet and in palmitic acid-induced HepG2 cells, highlighting the critical role of the GALR2 signaling pathway in spexin’s ability to improve fatty liver disease." (PMID 37180164, 2023). "Spexin, a neuropeptide in the galanin family, has been shown to activate GALR2/GALR3 (but not GALR1) and mitigate diet-induced hepatic steatosis in vivo and in vitro by activating GALR2." (PMID 37180164, 2023).
head and neck squamous cell carcinoma (2 papers, 2022 to 2023). A squamous cell carcinoma that arises from any of the following anatomic sites: lip and oral cavity, nasal cavity, paranasal sinuses, pharynx, larynx, and salivary glands. "Galanin receptor 2 (GALR2) plays a significant role in the progression of head and neck squamous cell carcinomas (HNSCC)." (PMID 35267186, 2022). "Galanin (GAL) stimulates a variety of signal transduction and integration pathways by activating its receptors GALR1, GALR2, and GALR3,14, 15 and thus far, GALRs have been found to be the most effective markers for predicting the prognosis of head and neck squamous cell carcinoma (HNSCC) patients." (PMID 36039037, 2023).
Anorexia (1 paper, 2022). Lack of desire to eat (loss of appetite). "In this study, we report that GALR2 is involved in SPX’s effects on leptin-induced anorexia and POMC expression." (PMID 35204737, 2022). "Together, these findings indicate that GALR2 is involved in SPX’s effects on leptin-induced anorexia." (PMID 35204737, 2022). "Thus, we sought to identify whether SPX action on leptin-induced anorexia is mediated via GALR2 and/or GALR3." (PMID 35204737, 2022).
anxiety disorder (1 paper, 2016). A category of psychiatric disorders which are characterized by anxious feelings or fear often accompanied by physical symptoms associated with anxiety. "Taken together, the GALR2-specific agonist with increased stability can greatly help delineation of GALR2-mediated functions and be very useful for treatments of anxiety disorder." (PMID 26907960, 2016).
cognitive decline (1 paper, 2024). "The significant role of GALR2 is emphasized, suggesting new potential therapeutic strategies for cognitive decline." (PMID 38549164, 2024). "The data from this study support the potential therapeutic utility of modulating GALR2 and NPY1R receptors in addressing cognitive decline associated with aging." (PMID 38549164, 2024).
colon cancer (1 paper, 2008). "Similarly NKX2-5, SPOCK2, SLC16A12, DPYS and GALR2 are candidate biomarkers for colon cancer (methylation range 60%–95%) and GALR2 hypermethylation showed a sensitivity of 85% and specificity of 95%." (PMID 18446232, 2008). "For example, most prostate and colon cancer cell lines showed hypermethylation at FOXN4 and GALR2, but primary prostate cancers showed lower frequency methylation compared to primary colon cancer." (PMID 18446232, 2008). "In a panel of 20 colon cancer cases, all these genes except IRX5, TFAP2E and TFAP2C showed significantly higher methylation in cancer by t-test analysis (P<0.001 for NKX2-5, DPYS SPOCK2, GALR2 and SLC16A12; P = 0.008 for FOXN4)." (PMID 18446232, 2008).
demyelination (1 paper, 2012). "In contrast with GalR1 expression, the expression of GalR2 was increased 1.4- and 2.1-fold in WT and Tg mice, respectively, in the demyelination groups; expression of GalR2 increased 2.2- and 3.3-fold in WT and Tg mice, respectively, in the recovery groups." (PMID 22442732, 2012).
diabetic neuropathy (1 paper, 2024). A chronic, pathological complication associated with diabetes mellitus, where nerve damages are incurred due to diabetic microvascular injury involving small blood vessels that supply these nerves, resulting in peripheral and/or autonomic nerve dysfunction. "Further studies into the contribution of galanin receptor 2 to the diabetic neuropathy and the effects of spexin on pain sensory are required." (PMID 38919263, 2024).
endometritis (1 paper, 2021). An acute or chronic, usually bacterial infectious process affecting the endometrium. "The current report presents the action of endometritis on the GALR1 and GALR2 protein expression in the myometrium, and the importance of GAL, GALR1, and GALR2 in the contractile activity of a pig uterus with inflammation." (PMID 34203944, 2021).